LDHA (lactate dehydrogenase A)
Diseases named in the same sentence as LDHA in open-access papers (continued):
Sharing a sentence is not in itself a finding about the gene and the disease.
tumor (continued). "As assessed by IHC tumor staining, we found that MUC1-C and LDHA levels were decreased to a greater extent with the combination of GO-203 and DTX treatment." (PMID 40553569, 2025). "In proneural type tumor model, tumor size, volume, and weight were markedly reduced after the treatment with GAA-BSA NPs, surpassing the impact of GAA and LDHA inhibitor FX11." (PMID 39895794, 2025). "This creates a positive feedback loop wherein tumor-derived lactate promotes H3K18la modification, which subsequently elevates STAT1 and LDHA expression." (PMID 41208879, 2025). "This binding protected LDHA mRNA from degradation, resulting in the enhanced glycolysis in TNBC cells and promoting tumor cell growth and invasion." (PMID 40555877, 2025). "Lactate dehydrogenase A (LDHA) converts pyruvate to lactate, regenerating NAD+ and supporting the production of lactate, which acidifies the tumour microenvironment to promote invasion and immune evasion." (PMID 41154605, 2025). "Our findings collectively demonstrate a positive feedback mechanism wherein tumor-derived lactate promotes H3K18la-mediated STAT1 transcription, which enhances LDHA expression and lactate production." (PMID 41208879, 2025). "The results revealed significantly higher SOX12 expression in tumor tissues than in normal tissues, and the expression levels of YBX1 and LDHA were consistent with those of SOX12." (PMID 40593465, 2025). "In hypoxic microenvironments, tumour cells produce substantial lactate by upregulating LDH activity, with LDHA catalysing the conversion of pyruvate to lactate to support hypoxic metabolism." (PMID 41249152, 2025). "Dual targeting of LDHA and LDHB disrupted this metabolic interplay, reducing tumor growth and enhancing radiotherapy sensitivity in preclinical models." (PMID 41375052, 2025). "Epigenetically, PRL-3 promotes primary tumor proliferation and metastatic capacity by upregulating PKM2 and glycolytic enzymes such as Glut1, HK2, and LDHA, collectively enhancing glucose uptake and lactate production." (PMID 40842995, 2025). "In tumor cells, glycolysis facilitates the conversion of excess pyruvate and NADH into lactate and NAD+ through the action of lactate dehydrogenase A (LDHA), thereby contributing to ATP production to some extent." (PMID 40137165, 2025). "The current work found that the downstream targets of HIF-1α activity, metabolic markers Ang2, GLUT1, LDHA, and PDK1, which equip the tumor for survival and growth under hypoxic conditions, were also downregulated by anlotinib plus bevacizumab." (PMID 41041327, 2025). "By targeting enzymes such as LDHA, GLUT1, HK2, PKM2, GLS1/2, FASN, ACLY and ACC, researchers have demonstrated the feasibility of disrupting tumor bioenergetics and biosynthetic machinery." (PMID 40941984, 2025). "We also found that FGFR4 and related metabolic genes (SLC2A1, LDHA, PFKL) were upregulated in tumors and FGFR4 high-expression groups, suggesting FGFR4's role in tumor metabolism." (PMID 40091020, 2025). "In some TNBC cases, stromal cells exhibit glycolytic activity to supply lactate to tumor cells (reverse Warburg effect), with low GLUT1/MCT4 in tumor cells, high MCT4 in the stroma, and elevated LDHA driving metastasis." (PMID 40723842, 2025). "This study examined how EMSY expression regulates glycolysis in tumor cells and its interaction with the beta-catenin/TCF signaling pathway in modulating LDHA expression levels." (PMID 41023769, 2025). "In this study, we demonstrate that pharmacological inhibition of LDHA using FX11 effectively impairs tumor growth and metastatic progression in PTC models, supporting LDHA as a potential therapeutic target within the SOX12-YBX1-LDHA signaling axis." (PMID 40593465, 2025). "Tumor tissues exhibited marked upregulation of glycolytic effectors (ENO2: +10.3-fold, LDHA: +8.7-fold), while obese adipose demonstrated immune activation signatures (FCGR2A: +6.1-fold, C1QC: +5.4-fold)." (PMID 41199823, 2025).
tumor (continued). "This was accompanied by increased tumor tissue expression of c‐Myc, Ki‐67, MCT1, LDHA, and PD‐L1, as well as decreased CD8+ T‐cell infiltration and granzyme B expression." (PMID 39220105, 2024). "The RGD decoration endows the nanoassembly with active tumor-targeting capabilities, facilitating efficient delivery of both DOX and LDHA siRNA to the tumor site." (PMID 39479443, 2024). "Activation of LDHA expression can be facilitated by the transcription factors c‐Myc14, 35, 36, 37 or HIF‐138, 39 in different tumour contexts." (PMID 39021353, 2024). "In this study, expression of LDHA and SLC16A3 was significantly higher in the EGFRHIGH/METHIGH subcluster of HNSCC PDX tumor compared to the EGFRLOW/METLOW subcluster (P < 0.05)." (PMID 38916448, 2024). "Lactate dehydrogenase A is a key enzyme in the metabolism of L‐lactate, and high levels of the LDHA isoform have been detected in muscle and tumours." (PMID 39417674, 2024). "A downregulation of LDHA activity results in decreased lactate levels in the TME and thereby attenuates tumor progression in preclinical models, and restores anti-tumor immune cell functions." (PMID 38229111, 2024). "As expected, acetate supplementation under low‐glucose conditions enhanced the expression of PD‐L1, cyclin D1, LDHA, and MCT1, MCT1‐dependent acetate uptake, lactate production, and tumor cell proliferation." (PMID 39220105, 2024). "LDHA, as the final enzyme in the glycolytic pathway, plays a crucial role in PDAC tumor growth and metastasis, impacting the number of MDSCs and the anti-tumor capacity of natural killer (NK) cells in the TME." (PMID 39343933, 2024). "Specific inhibition or knockdown of LDHA and HIF1A can restore sensitivity to therapeutic agents such as bortezomib and can also inhibit tumor growth induced by altered metabolism." (PMID 39025844, 2024). "Hypoxia has been found to enhance lactate production and tumor growth through activation of HIF1-α, GLUT1, HK2, PKM2, PDK, ENO1 or LDHA." (PMID 38233839, 2024). "Subsequently, utilizing machine learning techniques, we constructed the PIS model, comprising marker genes of CKS1B+ tumours (RHOV, ANLN, DEAR, PSMB7, KRT8, LDHA)." (PMID 38946232, 2024). "Activation of LDHA was closely related to phosphorylation of LDHA at Tyr10 by SRC or HER2, promoting cell invasion and tumor cell metastasis, and was correlated with poorer prognosis." (PMID 38301894, 2024). "This metabolism enrichment highlighted enzymes at the interface between glycolysis (GAPDH, ENO1, LDHA) and one-carbon metabolism (TYMS, SHMT2, MTHFR, MTHFD1), further confirming the importance of these two pathways in CIMP tumours." (PMID 38540202, 2024). "This includes increased expression of GLUT family members that import more glucose into tumor cells, as well as rate-limiting enzymes like hexokinase 2 (HK2) and lactate dehydrogenase A (LDHA)." (PMID 39273409, 2024). "IHC showed that the amounts of LDHA and NBS1 K388 lactylation were increased in the NAC-resistant tumours." (PMID 38961290, 2024). "Transcriptomic analysis was conducted on 725 BC samples, categorized by tumor grade, to explore the expression patterns of FASN and LDHA across the progression of the disease." (PMID 39044184, 2024). "Experimental data revealed that lactate dehydrogenase A (LDHA) knockdown inhibited proliferation and migration in iCCA cell lines and tumor growth in immunocompetent mice." (PMID 38627278, 2024). "In this process, LDHA is a crucial player in ATP production and regeneration of oxidized NAD necessary for proliferation and invasion of tumor cells." (PMID 39582531, 2024). "Each of these genes controls key steps in regulating metabolic homeostasis, and their expression is dysregulated in tumour cells and HCC, with LDHA typically upregulated and LDHB downregulated." (PMID 38710924, 2024). "Using the lactate dehydrogenase A (LDHA) inhibitor NCI-737 results in a twofold increase of stem cell memory T cells and improved anti-tumor responses." (PMID 38987856, 2024).
tumor (continued). "In tumor cells, glycolysis converts excess pyruvate and NADH into lactate and NAD+ via lactate dehydrogenase A (LDHA) to produce ATP to some extent." (PMID 39420203, 2024). "This inhibitory effect is accompanied by a significant downregulation of key regulators of tumor progression, including hypoxia-inducible factor-1 alpha (HIF-1α), lactate dehydrogenase A, and genes involved in the epithelial-mesenchymal transition pathway." (PMID 38978503, 2024). "Lactate dehydrogenase A (LDHA) primarily catalyzes the conversion between lactic acid and pyruvate, serving as a key enzyme in the aerobic glycolysis pathway of sugar in tumor cells." (PMID 38731521, 2024). "LDHA@MIP-DSD is designed to inhibit LDHA activity, effectively deactivating TAFs and enhancing the ability of therapeutic agents to penetrate the tumor stroma, thereby gaining access to cancer cells." (PMID 39479443, 2024). "The levels of LDHA and NBS1 K388 lactylation were increased following NAC in patients with NAC-sensitive or NAC-resistant tumours." (PMID 38961290, 2024). "α-Hederin have been found to significantly regulate tumor metabolism, by inhibiting glycolysis and the expression of GLUT1, HK2, PKM2 and LDHA." (PMID 38362150, 2024). "Pyruvate kinase (PK) and lactate dehydrogenase A (LDHA) are two crucial glycolytic enzymes that facilitate this process, conferring a growth advantage for tumor cells." (PMID 38773429, 2024). "Our study indicates that 4EBP1/eIF4E is the major signaling that modulates tumor cell proliferation and metabolic pathways, such as PKM1 and LDHA/C, that directly contribute to tumor proliferation." (PMID 39325536, 2024). "In OS tumor tissues and cells, we also observed the high HK2 and LDHA expression at the protein levels." (PMID 38218855, 2024). "Significant ilQTLs, the majority of which of somatic origin, were identified in immune-relevant genes, including B2M, HLA genes, CANX, LDHA, PSMB2, and HNRNPR, which are known to affect the tumor immune landscape." (PMID 38773080, 2024). "To investigate the biological pathways involved by LDHA in LUAD, we performed KEGG enrichment analysis on tumor samples included in the TCGA dataset." (PMID 39680520, 2024). "Lactate dehydrogenase A (LDHA) is an important glycolytic metabolic enzyme that converts pyruvate into lactic acid, increasing tumor cells’ glucose uptake and lactic acid production." (PMID 39582531, 2024). "The enzyme lactate dehydrogenase A (LDHA), which is crucial for cell development, is typically overexpressed in tumor cells." (PMID 36814901, 2023). "We observed the expression level of LMRGs in different cell types, and we found that LDHA was mainly expressed in tumor cells and ACKR1+ endothelial, while LDHB was highly expressed in vSMC, tumor cells, mast cells, and CD8+ T cells." (PMID 37795453, 2023). "Lactate dehydrogenase A (LDH-A) is the key enzyme in the Warburg’s effect, suggesting that tumor cells are more likely to undergo glycolysis than oxidative phosphorylation, despite existing in an aerobic environment." (PMID 38112846, 2023). "Among them, LDHA and LDHB are the significant components of LDH, which mediate the metabolic plasticity of tumor cells." (PMID 37547725, 2023). "Our study provides insight into the lactate-mediated crosstalk among tumor cells, CAFs, and immune cells in the TME and a rationale for the therapeutic strategy of targeting LDHA in glycolytic PDAC." (PMID 37733442, 2023). "Further, cell line experiments showed a significant increase in LDHA expression and a significant decrease in LDHB expression in the tumor cell lines ACHN, 786-O, and OS-RC-2 relative to the human normal renal epithelial cell line HK2." (PMID 37795453, 2023). "Consistently, the knockout of LDHA/LDHB in mouse models reduces the numbers, the expression of CD80 and MHC-I, and the antigen cross-presentation ability of tumor-infiltrating DCs." (PMID 37895048, 2023).
tumor (continued). "In particular, we identified a specific signature of glycolysis-related genes in BRAF-like tumours, which display the overexpression of SLC2A1, SLC2A3, HK3, PFKFB3, PKM, LDHA and SLC16A3 (alias Mct4, the membrane channel regulating lactate efflux)." (PMID 37198319, 2023). "In the current study, we detected LDHA and LDHB expression using public databases and WB analyses, explored their prognostic role in ccRCC using TMA, then revealed the tumor-immune interaction of LDHA/LDHB in ccRCC using TIMER2 and TISIDB databases." (PMID 37547725, 2023). "This reveals a new way in which lactic acid metabolism affects tumor immune microenvironment, and provides a new idea for developing new tumor immunotherapy strategies targeting lactic acid metabolism (such as MCT1, LDHA)." (PMID 37221594, 2023). "We explored the expression levels of four major lactate dehydrogenase (LDHA, LDHB, LDHC, and LDHD) and found that LDHA was significantly higher expressed in tumor tissue-derived cells and LDHB was higher expressed in normal tissue-derived cells." (PMID 37795453, 2023). "Similar to miRNAs, lncRNAs can also directly or indirectly regulate the activity of glycolytic enzymes, such as LDHA, PGK1, and PFKFB, in tumor cells." (PMID 37204526, 2023). "Reduced LDHa and cMYC expression in this study complements our previous findings that low doses of NK3.3EVs inhibit tumor cell proliferation." (PMID 38201518, 2023). "LDHA, PGM2 and the phosphorylated form of pyruvate kinase M2, the level of which is high in tumor cells, are all less expressed." (PMID 36674794, 2023). "In mouse cancer models, knockout of LDHA, LDHB, or knockout alone can inhibit tumor growth, highlighting their key role in tumor metabolism." (PMID 36875841, 2023). "As LDHA and LDHB participate in tumor cell metabolism and adaptation to detrimental cellular conditions, these enzymes are reportedly involved in tumor pathogenesis and progression." (PMID 37547725, 2023). "We also performed IHC analysis of SW480 xenograft tumor tissues and confirmed that the protein levels of the glycolytic enzymes GLUT1, GLUT4, HK2, LDHA and LDHB were lower in xenografts from PROX1 knockdown cells than in those from control cells." (PMID 36594098, 2023). "In CD8+ T cells, decreased NFATC1 expression reduces IFNg production, whereas inhibiting lactate dehydrogenase A (LDHA) reduces intracellular acidification and restores CD8+ T cell function and tumor infiltration." (PMID 37842241, 2023). "Then, survival analysis indicates that a high expression of SLCA6A3, SLC16A1, and LDHA and a low expression of LDHB are recognized as a tumor progression promotor in some tumors." (PMID 37122693, 2023). "The relationship to immune infiltration of LDHA and LDHB genes was further investigated using tumor immune estimation resource 2 (TIMER2) and Tumor-Immune System Interactions and DrugBank (TISIDB) databases, respectively." (PMID 37547725, 2023). "The expression of lactate dehydrogenase A (LDHA), which regulates lactate production, was a poor prognostic factor for patients with PDAC, and LDHA depletion suppressed tumor growth in a CAF-rich murine PDAC model." (PMID 37733442, 2023). "The LDHA, LDHB, LDHL, and hicD genes are involved in this pathway and exchange metabolic fuel with the tumor stroma, making them promising targets for CRC chemotherapeutic drugs." (PMID 37998446, 2023). "Public databases and WB analyses demonstrated higher LDHA and lower LDHB in ccRCC than in non-tumor tissues." (PMID 37547725, 2023). "Increased expression of LDHA that enhances lactate production induces EMT in tumor microenvironment and promotes tumor metastasis." (PMID 36735787, 2023). "In particular, ablation of CD44 lowered the LDHA-to-LDHB ratio, promoting mitochondrial respiration, while overexpression of CD44 increased the LDHA-to-LDHB ratio, enhancing lactate glycolysis and the Warburg effect in tumor cells." (PMID 37894408, 2023).
tumor (continued). "We observe similar changes in MCT4, LDHA, and LDHB between tumours with primary Gleason patterns 3 and 4 in an independent TCGA cohort." (PMID 35075123, 2022). "elucidated that LDHA upgrades RCC tissues and facilitates tumor migration and invasion through epithelial–mesenchymal transition." (PMID 35250999, 2022). "Next, the tumor tissues were sectioned and stained, and similarly, the results confirmed high expression of HIF-1α and glycolysis-related genes like LDHA, HK2, PKM2 in the control group and low expression in the shFAM83A-AS1 LUAD." (PMID 35002507, 2022). "We detected the expressions of glycolytic enzymes and membrane transporters, including GLUT1, HK2, PKM2, LDHA, and MCT4, in subcutaneous transplantation tumor models from WT and 5-FU-R HCT8 cells by IHC." (PMID 34998404, 2022). "In HCT116 Cells, wogonin inhibited the expression of HIF-1α and glycolysis-related proteins (HK2, PDHK1, LDHA) by inhibiting the PI3K/Akt signaling pathway, reduced glucose uptake and lactate production to combat drug resistance of tumor cell." (PMID 36339566, 2022). "Compared to LDHA, LDHB is expressed only in certain types of tumors, and its role in tumor progression is not fully understood." (PMID 36551514, 2022). "LDHA converts pyruvate and NADH to lactate, which provides an acidic microenvironment for tumor growth, while also contributing to the EMT process." (PMID 35936690, 2022). "Similar results have also been found from the two double KO cells in the LDHA/LDHB genes that completely block glycolytic pathways, but leave a low growth inhibitory effect in tumor cells, indicating cancer cell’s metabolic plasticity." (PMID 36077431, 2022). "And LDHA was identified as a transcription target of the oncogene MYC and was required for enhanced glycolysis and malignant potential of tumor cells." (PMID 36138435, 2022). "The expression of LDHA and LDHB is determined by the oxygen content of the tumor microenvironment, representing the glycolysis and oxidative phosphorylation levels, respectively." (PMID 36620597, 2022). "Notably, genes associated with the glycolysis/gluconeogenesis pathway including LDHA —whose overexpression in cancer is associated with proliferation and malignancy— and several glycolytic genes (e.g. HK1, VDAC1, and VDAC2) were only upregulated in LB fHER2− tumours and derived CLs." (PMID 36220861, 2022). "One study suggested that tumors with elevated lactate dehydrogenase A (LDHA) levels are more prone to immune evasion, and therefore tumor progression occurs due to limited anti-tumor mechanisms." (PMID 36330529, 2022). "This included measurement of the membrane transporters of pyruvate and lactate (MCT1, MCT4) and mRNA for the enzymatic subunits that catalyse the exchange between the two molecules (LDHA, LDHB), within tumour and stromal cells." (PMID 35075123, 2022). "Quinoline-3-sulfonamides and Galloflavin, which are inhibitors of LDHA, can inhibit HCC tumor proliferation." (PMID 36686771, 2022). "Dual therapy with the LDHA inhibitor, FX11, and the autophagy inhibitor, hydroxychloroquine (HCQ), had a synergistic effect on apoptosis in vitro and significantly reduced tumor growth in mouse models." (PMID 35846375, 2022). "For tumours that are significantly LDH-dependent genetic or pharmacological inhibition of LDHA effectively reduces cancer cell glycolytic flux and NADH/NAD ratio, and results in cancer cell apoptosis." (PMID 36578477, 2022).